FAM27E3 (family with sequence similarity 27 member E3)
Synonyms: MGC42630; FAM27A2; FAM27B
Gene: Long non-coding RNA gene on chromosome 9 (67,676,480 to 67,726,979, reverse strand). Ensembl gene ENSG00000274026.
Diseases named in the same sentence as FAM27E3 in open-access papers:
FAM27E3 is named in the same sentence as 7 diseases in open-access papers, as found by Europe PMC text mining. Sharing a sentence is not in itself a finding about the gene and the disease. The quoted sentences say what the papers report.
thyroid cancer (2 papers, 2024 to 2025). "Collectively, these results suggested that silencing of FAM27E3 disrupts the proliferation, clone formation, and metastatic capabilities of thyroid cancer cells, highlighting its crucial role in maintaining oncogenic phenotypes." (PMID 40809847, 2025). "The expression of FAM27E3 was up-regulated in thyroid cancer, and the high expressions of FAM27E3 suggested poor prognosis." (PMID 39355254, 2024).
lymph node metastasis (1 paper, 2025). "Score analysis was used to identify the relationship between the FAM27E3 expression and lymph node metastasis." (PMID 40809847, 2025).
cancer (1 paper, 2025). A tumor composed of atypical neoplastic, often pleomorphic cells that invade other tissues. "FAM27E3, also known as FAM-interleukin-27 receptor subunit 3, is a potential drug target or biomarker associated with various diseases, including cancer, neurological disorders, and immune system disorders." (PMID 40809847, 2025). "FAM27E3 plays a crucial role in physiological processes such as embryonic development, wound healing, and tissue regeneration, while also being involved in pathological processes like tissue fibrosis and the progression of malignant tumors." (PMID 40809847, 2025). "We then explored the effect of FAM27E3 expression inhibition on the behaviors of cancer cells." (PMID 40809847, 2025).
tumor (1 paper, 2025). "These collective findings indicate that FAM27E3 may enhance tumor stemness through EMT to promote lymph node metastasis." (PMID 40809847, 2025). "Additionally, FAM27E3 promotes EMT, facilitating tumor cell invasion and migration to distant tissues, as well as conferring stem-like properties upon migrated tumor cells that contribute to the formation of macroscopic metastatic lesions and the development of multidrug resistance." (PMID 40809847, 2025).
FAM27E3 also shares sentences with these, for which no sentence is quoted: immune system disorder (1 paper); neurological disorders (1); papillary thyroid carcinoma (1).